CTSB (cathepsin B)
Diseases named in the same sentence as CTSB in open-access papers (continued):
Sharing a sentence is not in itself a finding about the gene and the disease.
tumor (continued). "Salivary levels of Cathepsin B were significantly increased with p value (< 0.001) in patients of OSCC as compared to control group according to both histological grades and tumor size." (PMID 35260133, 2022). "In our study, the levels of salivary Cathepsin B were determined in OSCC patients in different histological grades and according to tumor size." (PMID 35260133, 2022). "Interplay between CTSB and NLRP3 inflammasome in tumor-infiltrating MDSCs results in IL-1 β production and pro-tumor immune response." (PMID 35277559, 2022). "The FRRG-MMAE nanoparticles efficiently accumulate within the tumor tissues owing to the enhanced permeability and retention (EPR) effect and inhibit the tubulin polymerization by releasing free MMAE in the cathepsin B-overexpressed tumor cells." (PMID 36297566, 2022). "For instance, cAC10-vcMMAE, constructed with anti-CD30 monoclonal antibody (cAC10), cathepsin B-specific cleavable valine-citrulline (VC) dipeptide linker, and MMAE, has shown highly selective therapy for the tumor treatment with minimized toxicity." (PMID 36297566, 2022). "Cathepsin B is a lysosomal cysteine protease that binds to ANX II and is detected on the cell surface of tumor cells." (PMID 34462873, 2022). "It was observed that salivary levels of Cathepsin B were increased significantly with p value (< 0.001) in patients of OSCC according to both histological grades and tumor size as compared to control group." (PMID 35260133, 2022). "While intracellular CTSB and CTSD have been demonstrated to be pro-apoptotic, intracellular CTSS has been found to be anti-apoptotic in HCC (thus, tumor promoting)." (PMID 36289617, 2022). "Cathepsin B (CTB) is highly expressed in tumor cells, and it can regulate the release of peptide drugs in the tumor site." (PMID 36559102, 2022). "After being translocated into lysosomes, the tetrapeptide linker can be cleaved by cathepsin B and the released PTX was transported into the cytoplasm, leading to effective tumour suppression." (PMID 33888701, 2021). "H-1PV treated patients displayed an increase in tumor-infiltrating cytotoxic T cells, induction of cathepsin B, and the expression of IFN-γ and IL-2, among other cytokines within the tumor microenvironment." (PMID 33066689, 2020). "Cathepsin B (CTSB) showed highest expression in PTC cells compared to other cell lines, and CTSB levels in tumor samples were higher than that seen in normal tissue." (PMID 33333840, 2020). "Studies have also found that cathepsin B-mediated proteolysis of DAB2, a tumor suppressor, induces cell entry into autophagy, promotes metastasis." (PMID 33335896, 2020). "AMS36 selectivity toward cathepsin X was also reported for tumor tissues, whereas in other tissues such as rat liver and kidney, a significant cross-reactivity of AMS36 with cathepsin B inhibition was observed." (PMID 33328882, 2020). "The increased mRNA expression exhibited a strong positive correlation with enzyme activities of both these proteases in tumor tissues, thereby suggesting the role of increased mRNA levels in elevating the expression of CTSL and CTSB." (PMID 31824841, 2019). "Because cathepsin B (CTBS) plays a pivotal role in the release mechanism, its mRNA expression was determined in patient derived tumor samples." (PMID 31484396, 2019). "CTSB supports CSC function and maintains tumor cell survival through degradation of ECM, modulation of immune responses, and regulation of autophagy." (PMID 30796200, 2019). "IF IHC staining demonstrated the expression of both cathepsin B and cathepsin D by the OCT4− cells within the tumor nests and the OCT4+ CSC subpopulation within the peritumoral stroma." (PMID 30177970, 2018). "Low pH has been shown to stimulate the release of Cathepsin B and MMP9, both of which accelerate tumor cell invasion." (PMID 29482580, 2018).
tumor (continued). "It has been suggested that the proteolytic action of cathepsin B contributes to the infiltrative nature of GBM by destroying components of the extracellular matrix, enabling detachment and infiltration of tumor cells into surrounding tissues." (PMID 28611989, 2017). "The level of expression of cathepsin B and cathepsin D in GBM has been shown to have a positive correlation with tumor aggressiveness and cancer prognosis, inferring a crucial role for the proteins in the biology of IDHWGB." (PMID 28611989, 2017). "The presence of CTSB and CTSD in the serum of the patients with NPC correlated with the tumor node metastasis (TNM) scores (p = 0.001)." (PMID 26995190, 2016). "Our previous studies showed that CTSB and CTSD are highly expressed in NPC metastatic tissues, and they increased cell motility and invasion, and promoted NPC tumor metastasis." (PMID 26995190, 2016). "The results showed that CTSB expression, serum AFP, tumor size, tumor recurrence and stage were recognized as independent prognostic factors of survival." (PMID 26896959, 2016). "Similar to what we observed as regards cathepsin B secretion, HGF and EGF-induced tumor cell invasion and motility were also significantly reduced following treatment with niclosamide." (PMID 26784896, 2016). "Furthermore, as determined by immunohistochemistry, the incidence of CTSB protein expression in poorly differentiated carcinomas was significantly higher than that in well-differentiated tumors, suggesting that high level of CTSB expression was related to poor tumor differentiation." (PMID 26896959, 2016). "In vitro and in vivo experiments demonstrated that over-expression of CTSB in MHCC-97 L cells promoted cell invasion and tumor progression ability." (PMID 26896959, 2016). "One of these is cathepsin B (CTSB), which plays a key role in facilitating tumor progression, growth, invasion and metastasis." (PMID 26562785, 2015). "Gocheva and colleagues found that the depletion of TAM-derived cathepsin B and S impaired tumor invasion, signifying the important role of TAM-derived proteases in tumor invasion." (PMID 25125485, 2014). "Cathepsin B, a cysteine protease, and MMP-9 have been shown to participate in tumor growth, invasion, and angiogenesis in GBM; RNA interference was effective in suppressing this phenotype, suggesting a potential therapeutic application." (PMID 23658650, 2013). "At the termination of the experiment, tumor volume in the four groups reached 853.401 ± 187.3, 782.39 ± 153.1, 771.904 ± 139.2, 373.078 ± 82.1 mm3 for PBS, Lipo, or NC, CTSB-shRNA, respectively (P > 0.05)." (PMID 24139065, 2013). "Among others, overexpression of serpin H1, F-actin capping protein subunit beta (CAPZB), macrophage capping protein (CAPG), villin 2 (EZR), and cathepsin B (CTSB) are known to promote cell motility and invasion in tumor tissues." (PMID 21305022, 2011). "CtsZ provided by tumor-associated macrophages is identified as a compensatory protease that can regulate the acquired tumor-promoting function of lesions lacking CtsB and CtsS." (PMID 40129966, 2025). "Unlike MMPs, which function extracellularly, cathepsin B is a lysosomal protease, enabling the selective activation of prodrugs and ADCs within tumor cells." (PMID 40871003, 2025). "In addition, visible-light-triggered prodrug nanoparticles (LT-NPs) combine verteporfin, a cathepsin B-cleavable peptide, and doxorubicin (DOX) for tumor-specific delivery and immunogenic cell death." (PMID 40520550, 2025). "It was also shown that cathepsin B expression was positively correlated with lymph node metastasis and higher tumor stage, but not with tumor size and distant metastasis." (PMID 40766321, 2025). "Overexpression of CTSB, CALU, S100A6, LDHA, and HNRNPA1 in endometrial cancer tissues was validated by WB, and IHC showed an intense cytoplasmic and nuclear staining of S100A6 in tumor samples." (PMID 39194522, 2024).
tumor (continued). "The conjugate [8Lys(Dau=Aoa-GFLG)]-GnRH-III, in which Dau was connected to the side chain of Lys in position 8 through an aminooxyacetylated cathepsin B-labile GFLG spacer, showed significant tumor growth inhibition in s.c.-developed fast-growing C26 murine colon cancer-bearing Balb/c mice." (PMID 38339141, 2024). "Aposome was only activated in tumor cells due to the cancer-overexpressed cathepsin B with no toxicity observed in normal cells and immune cells." (PMID 39769944, 2024). "In particular cathepsin B (CTSB), L (CTSL), and S (CTSS) are used as targets for near-infrared (NIR) fluorescence imaging (FI), a technique that allows real-time intraoperative tumor visualization and resection margin assessment." (PMID 39331316, 2024). "GEF could only be released after sequential input of NIR and cathepsin B stimuli, and the ROS produced during PDT promoted the apoptosis of tumor cells and inhibited the activation of the bypass IGF1R signaling pathway." (PMID 39321294, 2024). "Interestingly BARD1, CTSB, and GSTP1 were all highly expressed in tumor samples from the TCGA dataset." (PMID 37727789, 2023). "Furthermore, the activation of extracellular stores of cathepsin B and D may induce extensive matrix destruction or remodeling through cascades of other enzymes, which might be a major factor in the development of cancer by encouraging the invasion and metastasis of tumor cells." (PMID 37334378, 2023). "Similarly, compound 3 significantly decreased cathepsin B activity in ACHN and Hepa-1c1c7 tumour cell lines at concentrations of 1.52 ± 0.13 nM and 1.76 ± 0.24 nM, respectively." (PMID 37233478, 2023). "Notably, the cooperative effect of the low dose of ApoLNPs, tumor-exclusive administration by MSC guidance, and the cathepsin B-specific activation of the prodrug significantly lessened the systemic toxicity." (PMID 37845762, 2023). "In the primary tumor, cathepsin B derived from tumor cells rather than macrophages promotes cancer progression, while at the metastatic site stromal-derived cathepsin B seems to be the main driver of tumor progression." (PMID 36002710, 2023). "Moreover, the treatment of tumor-bearing mice with LCL521, a lysosomotropic inhibitor of acid ceramidase, activates cathepsin B and cathepsin D, resulting in interrupted autophagy and ER stress." (PMID 35159308, 2022). "CTSB-PPP-based PDT results in effective cytotoxicity and therefore, holds promise as a therapeutic agent for achieving the highly selective destruction of cells with high proteolytic activity, for instance, in neoplasms." (PMID 35631388, 2022). "Our analysis showed that CTSB expression in the tumor tissues of patients without metastasis (M0) positively correlated with STFA expression (R = 0.764, p < 0.05)." (PMID 35563761, 2022). "Likewise, the TME acidic pH provokes changes in tumor cells’ morphology and MMPs’ expression; for instance, the formation of tumor cell filopodia and invadopodia with a rise in pro-MMP-2 and cathepsin B in these cell structures." (PMID 35720130, 2022). "In a murine squamous cell carcinoma model, CtsB knockdown failed to affect tumor progression while increased StfA expression in breast, liver, and brain cancer was associated with decreased survival." (PMID 35563761, 2022). "In support of this hypothesis chemotherapy-induced cathepsin B release demonstrated to activate NLRP3 inflammasome in MDSCs, curtailing anti-tumor immunity." (PMID 36032139, 2022). "In the case of cathepsin B and S, we observed a slight negative correlation between the amount of cathepsin and the surface area of the cancerous tumor." (PMID 36431239, 2022). "Z-M ADCN can specifically bind to HER2 which overexpressed in various cancer cells and enter tumor cells by endocytosis, then MMAE can be released through the degradation of valine-citrulline (Val-Cit) dipeptide group due to the cathepsin B enzyme in cancer cells." (PMID 34902075, 2021).
tumor (continued). "Therefore, the in situ albumin-bound Al-ProD greatly enhances tumor accumulation with prolonged in vivo half-life and induces a potent antitumor efficacy by selectively releasing free DOX in cathepsin B-overexpressed tumor cells." (PMID 35056979, 2021). "Interestingly, most tumor types exhibited weaker ACE2/TMPRSS2 and ACE2/CTSB correlations compared to normal tissue, whereas the ACE2/CTSL and ACE2/FURIN correlations in normal tissue are weaker than that of most cancer types." (PMID 33707526, 2021). "CTSB, CTSL, and FURIN expression was increased in most tumor types relative to normal tissue." (PMID 33707526, 2021). "Moreover, simultaneous ablation of CTSB and CTSZ leads to synergistic anti-tumoral effects with delayed tumor onset, reduced number and size of metastases, and improved histopathological scores." (PMID 32385587, 2021). "Moreover, the PROTAC function of SPNpro is specifically activated by a cancer biomarker (cathepsin B) to trigger targeted proteolysis of immunosuppressive indoleamine 2,3-dioxygenase (IDO) in the tumor of living mice." (PMID 34006860, 2021). "In order to enhance capivasertib delivery to oral tumor cells, capivasertib was dissolved and encapsulated into nano-matrix with the enzyme-cleavable peptidic linker GFLG, which is sensitive to the lysosomal enzyme CTSB for drug release." (PMID 32106632, 2020). "Cathepsin B‐responsive tetrapeptide GFLG for bridging pHPMA and PTX‐pHPMA polymer chains is cleaved in a tumor microenvironment, leading to generation of small MW polymeric segments and PTX release specifically in the tumor cells with an equivalent potency to free PTX." (PMID 32195104, 2020). "Lysophospholipids and adrenomedullin stimulate insertion of the channel into the plasma membrane, and the subsequent TRPV2-mediated Ca2+ influx increases invasiveness of tumor cells via the direct regulation of key proteases such as MMP2, MMP9, and cathepsin B." (PMID 31288452, 2019). "Unsurprisingly, cathepsin B appears to be non-uniformly expressed throughout the tumor but increased expressed at the border to the extracellular matrix." (PMID 31484396, 2019). "Moreover, the levels of mature-CTSB and mature-CTSD were decreased in tumor sample from high-dose treatment." (PMID 31186406, 2019). "Despite increasing evidence for its involvement in promoting invasive tumor grades, little is known about the role of cathepsin B in its RAS-related influence on tumorigenesis in non-invasive WHO grade I MG, which represent 80% of all tumors." (PMID 30949483, 2019). "Our demonstration of slowed tumor growth in the presence of CTSB knockdown implicates CTSB not only in VEGFR TKI resistance, but also as a potential novel target in treatment of RCC." (PMID 30796200, 2019). "Murine knock-out models have indicated that the absence of cathepsin B, S or L impairs tumor invasion." (PMID 30818851, 2019). "In contrast, overexpression of CTSBN298A in the shCTSB2 line failed to rescue the growth-inhibitory effects of CTSB knockdown (P = 0.94 for shCTSB2 tumor growth vs shCTSB2 + CTSBN298A tumor growth)." (PMID 30796200, 2019). "In contrast to the tumour samples that showed detectable p‐BRCA1 in etoposide‐treated animals, RD‐N noticeably inhibited the expression of p‐BRCA1, which was correlated with positively stained CTSB and elevated γH2AX in the samples." (PMID 30565390, 2019). "We observed that in each of the different human and murine tumor cell models, upon TMEM106B induction, the enlarged lysosomes are loaded with active cathepsin B as evident from the enhanced red fluorescence in the lysosomal vesicles and significant increase in florescence intensity." (PMID 30013069, 2018). "Targeting CTSB alone does not appear to abolish tumor growth, and this is probably because CTSB appears to have diverse functions and influence numerous pathways." (PMID 28881816, 2017).
tumor (continued). "Cysteine cathepsins, the most prominent one in cancer being cathepsin B, are involved in the degradation of the ECM proteins (type IV collagen, laminin and fibronectin), thus facilitating growth and invasion of tumor cells into surrounding tissue and vasculature." (PMID 28460472, 2017). "CTSB expression was correlated with positive lymph node metastasis (p = 0.007) and higher tumor grade (p = 0.008) but not with tumor size and distant metastasis." (PMID 27031837, 2016). "Besides CTSB, other CTSs, such as cathepsin D (CTSD), cathepsin L (CTSL) and cathepsin S (CTSS), showed highly expression in invasive tumor and increase motility of cancer cells." (PMID 27031837, 2016). "Furthermore, by univariate analysis of the Cox proportional-hazard model, CTSB expression, serum AFP, tumor size, metastasis/recurrence, and TNM staging were found to be associated with an increased risk of death by HCC." (PMID 26896959, 2016). "In agreement with previous in vitro and in vivo data, CTSB activation was observed only in H-1PV-infected tumor cells but not in the surrounding peritumoral tissue." (PMID 25954743, 2015). "Finally, the expression of cathepsin B (CTSB), a lysosomal cysteine protease, was found elevated in all stages of CRC, from early tumor initiation to metastatic lesions." (PMID 23965959, 2013). "Downregulation of MHC genes that are involved in antigen presentation, including HLA-B/-C/-F/-G, and genes responsible for antigen processing, CTSB and HSPA2, may facilitating tumor cell evasion of immunosurveillance and, hence, increase tumor cell survival." (PMID 23024765, 2012). "Moreover, in the tumor sections, the presence of the GLUT-1 and EGFR, as well as the expression of MMP-9 and Cathepsin B, was shown by immunohistochemistry as well as indicated by FLI." (PMID 22348134, 2012). "These include: increased expression of growth factor receptors (e.g., EGFR), elevated glucose metabolism and up-regulated glucose transporters (e.g., Glut-1) and an increased tissue proteolysis by the tumor, through upregulation of proteolytic enzymes such as MMP-2, -9 and cathepsin B and D." (PMID 22348134, 2012). "Cathepsin B had previously been shown to activate pro-uPA, a serine protease and member of the plasminogen cascade involved in ECM degradation, matrix metalloproteinase (MMP) activation, and tumor cell invasion." (PMID 22093547, 2011). "We speculate that CTSB expressed by tumor cells and localized in caveolae may promote IBC metastasis to lymph nodes by enhancing ECM degradation and tumor invasion." (PMID 21199580, 2011). "Our current findings show that cathepsin B and caveolin-1 were co-expressed in tumor cells of IBC patient samples and not in those of non-IBC patients." (PMID 22093547, 2011). "Thus, our data suggest that overexpression of cav-1 in IBC cells contributes to proteolytic events involving CTSB that lead to ECM degradation, tumor invasion and metastasis." (PMID 21199580, 2011). "In these previous studies, sets of genes associated with pathways such as apoptosis (e.g., bax, bcl-2), DNA damage repair (e.g., Ku80, GADD45, XRCC5), cell adhesion (e.g., ICAM-3), angiogenesis (e.g., HIF-1a), and tumor cell invasion (e.g., CTSL, CTSB) were identified." (PMID 20184742, 2010). "Transient transfection of cathepsin-B (Cath-B) and -L (Cath-L) resulting in expression levels comparable to those found in many tumours did not sensitise tumour cells to TNF-α-mediated apoptosis." (PMID 14562034, 2003). "Additionally, phototherapeutic nano-PROTACs, like those targeting COX-1/2 and activated by tumor-overexpressed cathepsin B, enhance tumor-specific protein degradation, reprogram the tumor microenvironment (TME), and stimulate immune responses, further suppressing tumor growth." (PMID 39649701, 2024). "Clinically, our data demonstrated that in HCC patients, elevated CTSB expression correlated with worse overall survival and increased cancer progression, but its expression was not correlated with tumor size." (PMID 37923799, 2023).